HIF1A (hypoxia inducible factor 1 subunit alpha)
Diseases named in the same sentence as HIF1A in open-access papers (continued):
Sharing a sentence is not in itself a finding about the gene and the disease.
glioma (continued). "We found that DT at clinically achievable concentrations, suppressed HIF-1α accumulation during hypoxic conditions in human GSC and established glioma cell lines." (PMID 28410215, 2017). "We used immunohistochemistry to evaluate the expression of HIF1α, MIF and CXCR4 in our glioma specimens." (PMID 29113309, 2017). "In fact, it is shown that HIF-1α regulates the expression of GLUT-3 and that their coexpression in glioma is significantly correlated with the tumor pathological grade." (PMID 29312541, 2017). "We selected glioma cell lines, U87MG and U251, to further examine the relationship between these two proteins, as they express higher levels of HIF1α protein than T98 or NHA." (PMID 28754121, 2017). "In this study we show evidence of anti-glioma and other functional effects of ACF, a potent FDA-approved HIF-1α inhibitor, proving for the first time, that this small molecule provides extraordinary benefit in survival when delivered locally." (PMID 29097800, 2017). "Our results show that ACF treatment interferes with HIF-1α -mediated pathways thereby reducing the hypoxia-induced overexpression level of PGK-1 and VEGF in glioma cell lines, both downstream targets of HIF-1α." (PMID 29097800, 2017). "Through the dedifferentiation and differentiation regulated by HIF1α and VEGF, both cell types are dynamic and thus promote glioma growth and increase malignancy." (PMID 28427209, 2017). "The expression of HIF1α, MIF and CXCR4 in clinical specimens (six normal brain tissues and twenty-five human glioma tissues) was positively correlated with the grade of glioma." (PMID 29113309, 2017). "Hypoxia also induces the expression of HIF1α, and ablation of HIF1α expression decreases the CD133+ population and inhibits the invasive capability of glioma cells." (PMID 28670569, 2017). "Our mechanistic studies revealed that Daam2 promotes glioma tumorigenesis via suppression of VHL, a classic tumor suppressor that promotes HIF1α degradation and inhibits Akt activity." (PMID 29053101, 2017). "Given its role as the central regulator of HIF1α, surprisingly little is known about the regulatory biology surrounding VHL and its role in glioma formation." (PMID 29053101, 2017). "As shown by HE staining, the U251 xenografts grew in a more compact manner and were more homogeneous compared with glioma specimens; however, IL6, STAT3 and p-STAT3, LC3B, and HIF1A staining was essentially similar." (PMID 27163161, 2016). "The expression levels of HIF-1α and LDHB were found to be increased in high-grade gliomas compared with low-grade gliomas." (PMID 26735579, 2016). "Expression of MAOB and HiF-1α is highly correlated, with a correlation coefficient (R2) of 0.33 (p = 0.0072) for GBM alone and 0.36 (p = 0.0045) in all the glioma." (PMID 26689994, 2016). "Three slides, bearing 20 GBM, 7 lower grade glioma and control human temporal brain tissue, were simultaneously prepared for MAOB, HiF-1α, GFAP immunohistochemical labeling/staining and were imaged in a single session, using identical microscope settings." (PMID 26689994, 2016). "The perivascular localization of HIF-2α+ cells appeared to be consistent with the previous finding that HIF-2α, in contrast to HIF-1α, was expressed by CD133+ glioma cells under normoxia or mild hypoxia." (PMID 26799577, 2016). "In glioma, and perhaps other cancers, we suggest that the high steady state peroxide levels inhibit FIH-1, increasing both total and active HiF-1α, which we found to be localized to the nucleus." (PMID 26689994, 2016). "Our results confirm that both HIF-1α and POSTN expression increased as the grade of the glioma increased." (PMID 27602954, 2016). "We found that HIF-1α expression, POSTN expression, and the infiltration of TAMs (CD11b+) and M2 type TAMs (CD206+) increased as the grade of the glioma increased." (PMID 27602954, 2016).
glioma (continued). "The expression of IL6, p-STAT3, HIF1A, and LC3B positively correlated with the WHO grade of glioma, and Pearson's or Spearman's rho rank correlation tests showed that IL6, p-STAT3, HIF1A, LC3B and grade were positively correlated." (PMID 27163161, 2016). "Taken together, these results demonstrate that IL6 expression correlates with the density of autophagic cells and HIF1A levels in high-grade (WHO III and IV) gliomas." (PMID 27163161, 2016). "To explore the connection between POSTN expression, GSLCs and hypoxia in gliomas, we examined the POSTN expression pattern in human GBM surgical specimens that exhibited different levels of HIF-1α." (PMID 27602954, 2016). "Both HIF-1α and HIF-2α have been shown to be crucially involved in the promotion of in vitro sphere formation, cell growth, and the survival of CD133+ glioma cells." (PMID 26799577, 2016). "These predictions strongly suggest redirecting the focus of glioma drug candidates on controlling the feedback between IGFBP2 and HIF1α." (PMID 25884993, 2015). "HIF-1α and VEGF expression were significantly reduced in gliomas from immunized mice compared with controls." (PMID 25849072, 2015). "We examined the expression of miR224-3p, HIF1α and LC3B in clinical glioma specimens and normal brain tissues." (PMID 26536662, 2015). "As reciprocal relation exists between PPAR and HIF-1α: and as HIF-1α is a key component in glioma progression, their role in regulating CIDEA expression in glioblastoma was investigated." (PMID 27551468, 2015). "In human glioma cells, activation of HIF-1α, a positive downstream target of mTOR, enhances CD133+ glioma-derived cancer stem cell expansion by increasing self-renewal activity and inhibiting cell differentiation." (PMID 25815458, 2015). "BNIP3 is a direct transcriptional target of HIF-1α, which has been shown to regulate BNIP3 expression in response to hypoxia and in glioma cells treated with ceramide." (PMID 24824755, 2014). "Previous studies have shown the importance of HIF-1α and VEGF in the regulation of angiogenesis in glioma." (PMID 24980823, 2014). "On the one hand, DHA treatment reduced hypoxia-induced HIF-1α activation and VEGF expression in multiple myeloma and C6 rat glioma cells resulting in reduced tumor cell growth and angiogenesis, respectively." (PMID 24904829, 2014). "This cytokine actually induces TLR4 expression, via hypoxia inducible factor 1-α (HIF-1α), which results in the elevation of HMGB1 in glioma cells." (PMID 25411122, 2014). "In glioma cells, IGF-1 induced TLR9 through HIF-1α signaling, mediated by Ras and calmodulin dependent kinase II (CaMK II)." (PMID 25411122, 2014). "There was a significant difference in the HIF-1α mRNA transcript levels between the 5 μmol/L ATRA group and the 10 μmol/L ATRA group in SHG44 glioma cells (P < 0.05)." (PMID 23554794, 2013). "We observed that ATRA significantly induced HIF-1α mRNA expression in U87 and SHG44 glioma cell lines." (PMID 23554794, 2013). "In this study, we investigated the effects of the inhibition of HIF-1α on cell survival and radiosensitivity in U251MG and U343MG glioma cells, using two different strategies." (PMID 21050481, 2010). "Although inhibition of HIF-1α under hypoxic conditions enhanced radiosensitivity of glioma cells U251MG and U343MG, the effects of HIF-1α inhibition on radiosensitivity under normoxic conditions were not obvious." (PMID 21050481, 2010). "The glioma cell lines U251MG and U343MG displayed comparable HIF-1α mRNA expression levels under normoxic and hypoxic conditions." (PMID 21050481, 2010). "SN38 inhibited HIF-1α and VEGF mRNA and protein expression of glioma cells in a dose- and time-dependent manner." (PMID 20414463, 2010). "When we analyzed glioma cell lines, we found that, under normoxic conditions, U251MG and U343MG cells expressed small amounts of HIF-1α protein." (PMID 21050481, 2010).
glioma (continued). "In this context, HIF-1α transcriptionally activates VEGF which in turn initiates and promotes glioma angiogenesis (see Mediators of glioma angiogenesis below)." (PMID 20414333, 2010). "We developed two HIF-1α chimeric reporter systems, HIF-1α/FLuc and HIF-1α(ΔODDD)/FLuc, to investigate the tightly controlled level of HIF-1α protein in normal (NIH3T3 and HEK293) and glioma (U87) cells." (PMID 19347037, 2009). "In our study, serum HIF-1α levels were significantly higher in the HGG and LGG groups, meaning that HIF-1α may be an indicator of malignancy and may also play a role in glioma development and progression." (PMID 40512281, 2025). "It was also reported that HIF-1α expression was greater in hypoxia-treated A172, U87, U251, and Hs683 glioma cells compared to non-hypoxia-treated cells." (PMID 40512281, 2025). "In summary, under hypoxia, HIF1α and HIF2α regulate downstream IGF1R expression in glioma cells." (PMID 40290443, 2025). "Collectively, the findings from patient 15 hint at the lack of a hypoxia-induced metabolic phenotype, supporting the observations of Kickingereder and colleagues of strong inhibition of HIF1A and decreased expression of HIF1α target genes in IDH1 mutant gliomas." (PMID 39816516, 2025). "Glioma studies show predominantly tumour-suppressive activity via TNFAIP2 and caspase pathways, yet upregulation can enhance proliferation and migration through FIH-1/HIF-1α signalling." (PMID 41379397, 2025). "Interestingly, we also found through analysis of the TCGA database that HIF‐1α and RIT1 are positively correlated in glioma tissues." (PMID 39833023, 2025). "In human glioma cells, STAT1 can abolish HIF-1a activity, thereby reducing VEGF-A expression." (PMID 40370455, 2025). "Notably, HIF-1α is also a potent activator of VEGF, which is also overexpressed in glioblastoma and serves as the predominant inducer of angiogenesis in gliomas." (PMID 41034696, 2025). "In this study, we established glioma cell lines with stable PAX6 overexpression and integrated bioinformatics, molecular, and animal model approaches to systematically investigate the regulatory relationship between PAX6 and HIF-1α." (PMID 41154694, 2025). "Moreover, the HIF1α- tenascin C (TNC) feedback loop has been identified as a key regulator of ECM stiffness and glioma aggression, with mutant IDH1 suppressing HIF1α expression and reducing TNC deposition." (PMID 40076738, 2025). "The mRNA expression level of HIF-1α was significantly elevated in glioma tissue compared with adjacent normal tissues (P < 0.01); HIF-1α mRNA expression was significantly elevated in U251, SHG-44, and U87 glioma cell lines when compared with normal brain cells (P < 0.01)." (PMID 38734702, 2024). "Moreover, Cu-ATSM uptake is noticeably greater in grade IV gliomas compared with grade III gliomas and correlates with HIF-1α expression, a marker of hypoxia." (PMID 38662225, 2024). "Additionally, glioma cluster 2 cells expressed selectins (LGALS1 and LGALS3), integrins (ITGB1), and glycosylation targets (VIM, TIMP1, HIF1A, and CD44)." (PMID 39333557, 2024). "Our results showed that the expression levels of FBXO22, HIF-1α, and VEGFA in high-grade gliomas were much higher than those in low-grade gliomas, while the expression level of VHL in high-grade gliomas was much lower than that in low-grade gliomas." (PMID 38519492, 2024). "Our results suggest that the malignant behaviors of glioma cells are suppressed by SHD and the mechanism may be closing on the inhibition of the PI3K/Akt-HIF1A axis." (PMID 39092253, 2024). "Finally, we confirmed that there are positive correlations among FBXO22, HIF-1α, and VEGFA expression in glioma patients." (PMID 38519492, 2024). "The outcomes include the abolishment of hypoxic stabilization of HIF-1α and HIF-1α-mediated cellular responses in glioma C6 cells, being hypothesized that cyclosporin A might limit adaptative responses to hypoxia." (PMID 38667760, 2024).
glioma (continued). "Additionally, IHC staining of TGFBI expression in 58 glioma specimens revealed a positive correlation between TGFBI and HIF1α." (PMID 39346536, 2024). "PX‐478, a HIF‐1α inhibitor, has been shown to inhibit the protein expression level and transcriptional activity of HIF‐1α, thereby exhibiting effective antitumour activity in various tumours, including nonsmall cell lung cancer, glioma and pancreatic cancer." (PMID 39107958, 2024). "Furthermore, knockdown of CLK1 In glioma cells (GL261) increased aerobic glycolysis and expression of HIF-1α via the AMPK/mTOR signaling pathway." (PMID 39742274, 2024). "For predicting hypoxia niches in glioma, the D* value showed a negative correlation with HIF-1α expression." (PMID 39906347, 2024). "We searched the TCGA and Rembrandt glioma datasets using the Gliovis platform and found that HIF-1α is overexpressed in GBMs compared to non-tumoral tissue." (PMID 38341408, 2024). "In the glioma model, HBO inhibited HIF1α and improved prognosis." (PMID 37790761, 2023). "We further examined whether RP58 regulates the expression of HIF‐1α and PHD3 in U251 glioma cells by overexpressing RP58 using lentivirus." (PMID 37701531, 2023). "Present study was purposed to figure out the expression level of mitochondrial sirtuins (SIRT3, SIRT4, SIRT5) and related genes (GDH, OGG1-2α, SOD1, SOD2, HIF1α and PARP1) in 153 glioma tissue samples and 200 brain tissue samples from epilepsy patients (taken as controls)." (PMID 36809279, 2023). "In glioma, POSTN may regulate resistance to anti-VEGF-A therapy by upregulating the expression of TGFβ1 and HIF1α." (PMID 37180146, 2023). "GSC gliomas showed significant heterogeneity and invasiveness on imaging, and exhibited strong expression of Ki-67, partial expression of EGFR and VEGF, and weak expression of MGMT and HIF-1α on immunohistochemical staining." (PMID 36591483, 2022). "In glioma cells, STAT6 negatively regulated HIF-1α expression via mTOR/S6K/S6 axis." (PMID 35600336, 2022). "DKC1 could upregulate the expression of N-cadherin, MMP-2, HIF1A, CDK2, and cyclin E, and the glioma cells with DKC1 knockdown exhibited low motility." (PMID 36437949, 2022). "FCM was used to detect the proportion of CD133+CD15+ cells after culturing CD133-CD15- glioma cells in 1% O2 for 7 days, and the results showed that both CD133 expression and CD15 expression were significantly decreased in HIF1α-ko and HIF2α-ko cells compared with vector cells." (PMID 34976166, 2022). "Gliomas have elevated monoamine oxidase B (MAOB), SP1, and HIF-1α levels." (PMID 36077352, 2022). "Furthermore, PX-478 helps in radiosensitization of hypoxic C6 glioma, HN5, and UMSCCa10 squamous cells and Panc-1 pancreatic adenocarcinoma cells by inhibiting HIF-1α in vitro." (PMID 36014432, 2022). "CD133-CD15- GL261 and primary glioma cells were cultured in 21% O2 or 1% O2, and the results showed that there was no HIF1α or HIF2α expression in the normoxic environment, but the cells in 1% O2 had much higher expression of HIF1α and HIF2α." (PMID 34976166, 2022). "HIF-1α combined with JAK1/2-STAT3 (Janus kinase 1/2-signal transducer and activator of transcription 3) axis could enhance the self-renewal of glioma stem-like cells." (PMID 35607406, 2022). "Our proposed model is consistent with previous studies reporting that AP-1 binding enhanced HIF-1α transcriptional activation of VEGF in other systems (e.g., glioma cells), suggesting AP-1/HIF-1α cooperativity for target gene activation in response to hypoxic stimulation." (PMID 36298843, 2022). "miR-23b affects the survival and invasion of glioma cells by targeting and modulating the von Hippel–Lindau (VHL), thereby inhibiting the Hypoxia-inducible factor 1a/vascular endothelial growth factor (HIF-1a/VEGF) pathway and b-catenin/Tcf-4 transcription." (PMID 36479040, 2022).
glioma (continued). "In addition, glutamate secretion and ATF4-mediated function of xCT represent a candidate mechanism for the promotion of angiogenesis in ATF4 overexpressing gliomas, besides the induction of VEGF and HIF-1α expression." (PMID 35409080, 2022). "Therefore, 2-HG generation and 2-OG depletion indirectly provide the stabilization of HIF-1α, leading to an increase in HIF-1α target genes, such as the vascular endothelial growth factor (VEGF), in IDH-mutant gliomas." (PMID 34356864, 2021). "Altogether, a regulatory axis consisting of OR7E156P, miR-143, and HIF1A, which is deregulated in glioma was identified, and the process of the OR7E156P/miR-143/HIF1A axis modulating glioma cell invasion through ZEB1 and HUVEC tube formation through VEGF was ascertained." (PMID 34422645, 2021). "Studies have found that downregulating the CLK1 gene in glioma GL261 cells can inhibit mitochondrial function, reduce AMPK phosphorylation levels, activate the mTOR signaling pathway, promote the upregulation of HIF-1α in tumor cells, and enhance the sensitivity of GL261 cells to chemotherapy drugs." (PMID 34568328, 2021). "Previous studies have shown that HIF2A and not HIF1A is differentially expressed on the glioma stem-like cells compared to non stem-like cells." (PMID 34489494, 2021). "Interestingly, the angiogenic and mesenchymal switch coincides with STAT3 upregulation, regulating HIF-1α and CAIX expression under hypoxia in glioma cells." (PMID 34073734, 2021). "Importantly, clinical analysis revealed higher levels of miR-301a expression in glioma samples with high HIF-1α levels and the percentage of serum exosomal miR-301a (low versus high) was distributed according to the HIF-1α immunohistochemistry score." (PMID 33535436, 2021). "In summary, we speculated that BMAL1 might be involved in angiogenesis in human glioma cells by regulating VEGF and ANG2 expression via HIF-1a pathway." (PMID 34815366, 2021). "Although HIF1α is highly expressed in both glioma stem and bulk tumor cells, its role has not been thoroughly evaluated." (PMID 34470658, 2021). "It has been demonstrated that the hypoxic microenvironment of glioma could up-regulate the expression of ANG2 and VEGF via HIF-1a pathway." (PMID 34815366, 2021). "We hypothesized that inhalational anesthetics might modulate the HIF-1α and MMP9 cell signaling/pathway in glioma cells via miRNA expression changes." (PMID 33919449, 2021). "However, a more recent study showed that IL-8 promoted glioma migration, invasion, and mesenchymal transition by regulating the STAT1/HIF-1α/Snail axis." (PMID 34276757, 2021). "Due to the efficient glucose uptake and glycolysis, glucose was deprived in the hypoxic lesions by glioma cells, resulting in Tregs relying on fatty acids for mitochondrial metabolism and migrating to glioma tissues in response to CCL22 in a HIF-1α-dependent manner." (PMID 34211978, 2021). "To determine whether our findings are clinically relevant, we stained glioma tissue sections (n = 50) for BATF2, SDF-1α, HIF-1α (hypoxia marker), CD14 (Mo-MDSCs marker), and CD33 (MDSCs marker)." (PMID 33452462, 2021). "It is upregulated in glioma cells under hypoxia, but it does not possess HREs activated by HIF-1α under hypoxic conditions." (PMID 34073734, 2021). "Hypoxia-induced HIF1A upregulation in glioma cells was significantly reversed by silencing OR7E156P, suggesting that OR7E156P might affect HIF1A, subsequently modulating glioma cell response to hypoxia." (PMID 34422645, 2021). "Whether HIF1α plays a critical role in GBM growth remains undefined, although HIF1α knockdown was shown to inhibit growth and invasion of glioma cell lines in vitro." (PMID 34470658, 2021). "Overall, our study revealed that HIF1A directly bond with HRE-3 in the region of FTL promoter to enhance its expression and FTL might act as a crucial gene that regulated EMT process of glioma." (PMID 32677981, 2020).